TBX3 (T-box transcription factor 3)
Diseases named in the same sentence as TBX3 in open-access papers (continued):
Sharing a sentence is not in itself a finding about the gene and the disease.
sarcoma (9 papers, 2016 to 2024). A usually aggressive malignant neoplasm of the soft tissue or bone. "Our findings suggest that TBX3 may be a candidate diagnostic marker and a common therapeutic target for a diverse range of sarcoma subtypes." (PMID 26900951, 2016). "Importantly, several of the top upregulated genes (FC > 5) were associated with sarcomagenesis and 57 of the upregulated genes in TBX3 hMSCs were present in the CINSARC (Complexity INdex in SARComas) database which contains 67 genes associated with sarcoma aggressiveness and poor prognosis." (PMID 35145908, 2021). "Previously, it has been shown that TBX3 cooperates with c-Myc to induce the transformation of sarcoma-initiating cells." (PMID 38909034, 2024). "Correlation between high nucleolin and TBX3 co-expression and poor survival was observed in sarcomas." (PMID 36291832, 2022). "The latest study reported that nucleolin is expressed with TBX3 in multiple sarcomas including RMS, and AS1411 exhibited anti-sarcoma activities with IC50 values of 5–18 μM." (PMID 36359210, 2022). "In these sarcomas, nucleolin is co-expressed with TBX3 to regulate p21CIP1 and p14ARF transcriptions." (PMID 36359210, 2022). "The c-Myc and TBX3 oncoproteins are overexpressed in several sarcoma subtypes including chondrosarcoma, liposarcoma and rhabdomyosarcoma where they exert tumorigenic effects." (PMID 35145908, 2021). "TBX3 was previously shown to promote migration and invasion of several sarcoma subtypes and here we reveal that, when overexpressed in hMSCs, TBX3 also promotes these oncogenic processes." (PMID 35145908, 2021). "Collectively our data provide evidence that TBX3 functions downstream of c-Myc in the transformation of hMSCs into sarcomas." (PMID 35145908, 2021). "Together, these findings extend our current knowledge of the role of TBX3 in CSCs and highlight the role of TBX3 in maintaining the stem cell population that contributes to tumourigenesis and its potential as a key initiator of sarcoma." (PMID 35145908, 2021). "T-box transcription factor 3 (TBX3) is upregulated by c-Myc in a host of sarcoma subtypes where it promotes proliferation, tumor formation, migration, and invasion." (PMID 35145908, 2021). "If the upregulation of TBX3 by c-Myc is a key molecular mechanism involved in transforming hMSCs to sarcomas, then one would expect that parental hMSCs will have lower levels of TBX3 than TBX3-driven sarcomas." (PMID 35145908, 2021). "To begin to explore the status of TBX3 in sarcomas we firstly analysed TBX3 expression in a panel of normal and transformed fibroblast cell lines by western blotting." (PMID 26900951, 2016). "Here we show that a diverse subset of soft tissue and bone sarcoma cell lines and patient-derived sarcoma tissues express high levels of TBX3." (PMID 26900951, 2016). "To this end, we transiently knocked down TBX3 using siRNA (small interfering RNA) in five histologically diverse sarcoma subtypes and performed scratch motility assays." (PMID 26900951, 2016). "Taken together, this study shows for the first time that TBX3 is overexpressed in several sarcoma subtypes and that it functions as either an oncoprotein or a tumour suppressor depending on the cellular context." (PMID 26900951, 2016). "In this regard, the transcription factors TBX2 and TBX3 are of particular interest because their overexpression in several carcinomas and sarcomas was shown to enhance cell proliferation, bypass senescence and apoptosis, and promote tumour formation, angiogenesis and metastasis." (PMID 39403898, 2024). "We hypothesize that the c-Myc/TBX3 axis is important in sarcomagenesis and that TBX3 overexpression will drive hMSCs into sarcomas." (PMID 35145908, 2021). "Together, our study reveals that TBX3 may be a driving factor for the initiation of sarcomagenesis and thus provides additional support for the hypothesis that targeting TBX3 for anti-sarcoma treatment may be a promising approach." (PMID 35145908, 2021).
sarcoma (continued). "Together, the data described indicate that the c-Myc/TBX3 oncogenic molecular pathway may be a key mechanism that transforms hMSCs into sarcomas." (PMID 35145908, 2021). "To explore whether the c-Myc/TBX3 axis exists in hMSCs we first investigated whether, as is the case in sarcomas, c-Myc transcriptionally activates TBX3." (PMID 35145908, 2021). "In addition, TBX3 is overexpressed in a myriad of carcinomas and sarcomas, where it contributes to multiple aspects of the oncogenic process." (PMID 32098189, 2020). "Our data showed that TBX3 represses TBX2 in RMS cell lines so we asked if this expression correlation could also be observed in additional sarcomas using available patient data." (PMID 30979887, 2019). "Together these findings provide evidence that the overexpression of TBX3 may be a feature of a wide range of sarcoma subtypes and that TBX3 impacts directly on their development as either an oncogene or a tumour suppressor." (PMID 26900951, 2016). "We next determined if this overexpression of TBX3 may be a feature of sarcomas and to this end we screened a panel of soft tissue and bone sarcomas for TBX3 protein." (PMID 26900951, 2016). "This suggested that TBX3 may play a key role in the development of different sarcoma subtypes by functioning as either an oncoprotein or as a brake to prevent tumour progression." (PMID 26900951, 2016). "Taken together, data from our chondrosarcoma and fibrosarcoma cell culture models provide compelling evidence for a novel tumour suppressor role for TBX3 in fibroblasts and suggest that TBX3 may play opposite roles in the development of sarcomas." (PMID 26900951, 2016). "Together, our data suggest that the upregulation of c-Myc and consequently TBX3 may be a key event that promotes sarcomagenesis, and that this event either on its own or in combination with other oncogenic hits may transform MSCs into sarcomas." (PMID 35145908, 2021). "Together, our study demonstrates that TBX3 promotes several cancer hallmarks in 2D- and 3D-hMSC models and future studies are required to investigate whether TBX3 alone can transform hMSCs into sarcomas in vivo." (PMID 35145908, 2021). "Furthermore, while c-Myc transcriptionally activates TBX3 in these sarcomas, whether TBX3 is a c-Myc target gene in MSCs, and whether the overexpression of TBX3 in MSCs can promote sarcomagenesis is still unknown." (PMID 35145908, 2021). "Indeed, we reveal that TBX3 may exhibit oncogene or tumour suppressor activity in sarcomas, which suggests that its role in cancer progression may rely on cellular context." (PMID 26900951, 2016). "Furthermore, we show that TBX3 may be a biomarker for the diagnosis of histologically dynamic sarcoma subtypes and that it impacts directly on their oncogenic phenotype." (PMID 26900951, 2016). "Furthermore, our data showing that depleting TBX3 inhibits the cancer phenotype of several sarcoma subtypes suggests that it may also represent a common target to treat diverse sarcomas." (PMID 26900951, 2016). "However, the status and role of TBX3 in sarcomas have not been reported." (PMID 26900951, 2016).
chondrosarcoma (8 papers, 2016 to 2024). A malignant cartilaginous matrix-producing mesenchymal neoplasm arising from the bone and soft tissue. "The effect of these mutations was assessed using luciferase assays where chondrosarcoma cells were co-transfected with the p21 promoter luciferase reporter construct and the pCMV empty vector, WT, S190A or S190E TBX3 expression constructs." (PMID 27110270, 2016). "Furthermore, in chondrosarcomas as well as in other cancers, TBX3 has been implicated in several oncogenic processes including promoting cell proliferation, tumour formation, migration and invasion which suggest that it must be regulating several other target genes." (PMID 27110270, 2016). "TBX3 was shown to promote proliferation, tumor formation, migration, and invasion of chondrosarcoma, liposarcoma and rhabdomyosarcoma cells." (PMID 35145908, 2021). "Omar Ret al., reported that COL1A2 affects cell migration of fibrosarcoma and chondrosarcoma by acting on TBX3." (PMID 33193601, 2020). "We further explore the significance of this overexpression using a small interferring RNA approach and demonstrate that TBX3 promotes the migratory ability of chondrosarcoma, rhabdomyosarcoma and liposarcoma cells but inhibits fibrosarcoma cell migration." (PMID 26900951, 2016). "Together these data suggest that the repression of p21 by TBX3 is a key downstream event in mediating the ability of TBX3 to promote proliferation of chondrosarcoma cells." (PMID 27110270, 2016). "Using rescue assays in TBX3 knockdown and overexpression chondrosarcoma cell culture models, the repression of p21 by TBX3 was shown to be physiologically relevant because it was required for TBX3-induced cell proliferation." (PMID 27110270, 2016). "We used the ATDC5 and SW1353 chondrosarcoma cell lines because we recently reported that TBX3 promotes their proliferation and we showed that this was accompanied by a decrease in p21 protein levels." (PMID 27110270, 2016). "Similar to what has been described for TBX3 in carcinomas we show that it directly contributes to the oncogenic phenotype of chondrosarcoma cells." (PMID 26900951, 2016). "We further explore this possibility by establishing and characterizing cell culture models in which TBX3 is either knocked down or overexpressed in chondrosarcoma and fibrosarcoma cell lines." (PMID 26900951, 2016). "As expected, whereas depleting TBX3 inhibited the migration of chondrosarcoma cells, ectopic overexpression of TBX3 promoted their migration." (PMID 26900951, 2016). "We recently reported that knocking down TBX3 inhibited proliferation of chondrosarcoma cells and resulted in the re-expression of key cell cycle regulators including p21." (PMID 27110270, 2016). "To explore if p21 is transcriptionally repressed by TBX3 we first compared the protein and mRNA levels of p21 in chondrosarcoma cells in which TBX3 was stably knocked down (shTBX3) to that of control cells (shCtrl)." (PMID 27110270, 2016). "To confirm this in our chondrosarcoma cell lines in which TBX3 was either stably knocked down or overexpressed, we performed scratch and transwell motility assays." (PMID 26900951, 2016). "This study provides a full characterisation of the repression of p21 by TBX3 in chondrosarcoma cells." (PMID 27110270, 2016). "We next determined the impact of TBX3 on anchorage-independent growth of chondrosarcoma cells using soft agar assays." (PMID 26900951, 2016). "Results from in vitro and in vivo assays reveal that, while TBX3 promotes substrate-dependent and -independent cell proliferation, migration and tumour formation in chondrosarcoma cells, it discourages fibrosarcoma formation." (PMID 26900951, 2016). "Together these results provide compelling evidence to support a role for TBX3 as an oncogene in chondrosarcomas." (PMID 26900951, 2016).
chondrosarcoma (continued). "Interestingly, c-Myc transcriptionally activates TBX3 by directly binding two E-boxes, and this regulation was shown to be important for promoting chondrosarcoma cell proliferation." (PMID 32098189, 2020). "Moreover, c-Myc upregulates TBX3 transcriptionally in chondrosarcoma cells through two E-box motifs." (PMID 32098189, 2020). "Importantly, we provide a full characterisation of the mechanism by which TBX3 represses p21 and we demonstrate that this is required for TBX3′s pro-proliferative role in chondrosarcomas." (PMID 27110270, 2016). "Furthermore, immunohistochemical analyses revealed that TBX3 was expressed in patient-derived fibrosarcoma, synovial sarcoma, liposarcoma, chondrosarcoma and rhabdomyosarcoma tissue sections." (PMID 26900951, 2016). "Indeed, compared with the normal human skin fibroblast cell lines, FG0 and DMB, TBX3 was highly expressed in chondrosarcoma (ATDC5 and SW1353), synovial sarcoma (SW982), liposarcoma (SW872) and embryonal rhabdomyosarcoma (RD) cell lines." (PMID 26900951, 2016). "The current study shows that p21 mRNA and protein levels increased when TBX3 was knocked down in chondrosarcoma cells and provides compelling in vitro and in vivo data to show that TBX3 directly represses p21 which is important for TBX3-induced cell proliferation." (PMID 27110270, 2016). "Importantly, we demonstrate using knockdown and overexpression experiments that p21WAF1 repression by TBX3 is biologically significant and required for TBX3-induced cell proliferation of chondrosarcoma cells." (PMID 27110270, 2016). "Significantly, chondrosarcoma and fibrosarcoma cell culture models in which TBX3 was either depleted or overexpressed revealed that while TBX3 contributes to cell proliferation, migration and tumour formation in chondrosarcoma cells, it has an inhibitory effect on these processes in fibrosarcomas." (PMID 26900951, 2016). "Therefore, before we engineered hMSCs to overexpress TBX3, we compared the status of TBX3 mRNA and protein in three adipose-derived hMSC cell lines (hMSC line 1-3) as well as chondrosarcoma (SW1353) and liposarcoma (SW872) cells by qRT-PCR and western blotting respectively." (PMID 35145908, 2021). "In this regard, it is important to note that human TBX3 negatively regulates the INK4A-ARF locus, and an inverse correlation between TBX3 and p14ARF was observed in chondrosarcomas and fibrosarcomas." (PMID 35145908, 2021). "Collectively these results suggest that the phosphorylation of TBX3 at SP190 regulates its ability to repress p21 and that this is an important determinant of its ability to promote proliferation of chondrosarcoma cells." (PMID 27110270, 2016). "Indeed, there is evidence to suggest that TBX3 may also repress p21 transcriptionally and we and others have shown an inverse correlation between the ability of TBX3 to promote proliferation of chondrosarcoma, mammary epithelial and hepatic progenitor cells and p21 levels." (PMID 27110270, 2016). "Alterations in cell cycle genes due to the upregulation of their transcription factor, such as c-Myc, Forkhead Box F (FoxF1/FoxF2), and T-box transcription factor 3 (TBX3), are frequently found in leiomyosarcoma, osteosarcoma, chondrosarcoma, synovial sarcoma, and Ewing’s sarcoma (EwS)." (PMID 37681936, 2023). "Based on the observation that the TBX3 S190E mutant had a reduced ability to bind and repress the p21 promoter, we hypothesised that this pseudo-phosphorylated TBX3 may not be able to promote chondrosarcoma cell proliferation." (PMID 27110270, 2016).
colorectal cancer (8 papers, 2020 to 2025). A primary or metastatic malignant neoplasm that affects the colon or rectum. "Our research reveals that the transcription factor TBX3, long recognized for its role in limb and heart embryogenesis, becomes aberrantly present in colorectal cancers (CRC)." (PMID 40343989, 2025). "We employed ICEBERG to map the full set of H3K4me3-marked regions, the targets of the co-factor β-catenin, and those of the transcription factor TBX3, in human colorectal cancer cells." (PMID 38499482, 2024). "This was also the case for SMAD4 in pancreatic cancer, TBX3 in colorectal cancer, or TSC2 in liver cancer." (PMID 36937541, 2023). "These include TBX3, which promotes epithelial to mesenchymal transition and predicts poor prognosis in colorectal cancer, and GBX2, which promotes growth of breast and prostate cancer cells." (PMID 34611476, 2021). "In this study, we show that TBX3 is functionally active in human colorectal cancer (CRC)." (PMID 40343989, 2025). "We applied ICEBERG to profile H3K4me3-marked regulatory regions, β-catenin and TBX3 targets in human colorectal cancer (CRC) cells, a context in which Wnt/β-catenin constitutes the main oncogenic driver and is subject of intense investigation in search of druggable mechanisms to treat disease." (PMID 38499482, 2024). "Fructus ligustri lucidi could enhance chemosensitivity and induce apoptosis via Tbx3 suppression in human colorectal carcinoma cells." (PMID 38466979, 2024). "Finally, TBX3 overexpression exacerbates the metastatic potential of Wnt-dependent human colorectal cancer cells." (PMID 32808927, 2020).
fibrosarcoma (8 papers, 2016 to 2025). A malignant mesenchymal fibroblastic neoplasm affecting the soft tissue and bone. "Unexpectedly, our study also revealed a novel role for TBX3 as a tumour suppressor in fibrosarcomas." (PMID 26900951, 2016). "In addition to its carcinogenic role, TBX3 has also been shown to function as a tumor suppressor in fibrosarcoma and liver cancer, suggesting that the role of TBX3 is cancer-specific 67,68." (PMID 39897553, 2025). "Importantly, we provide evidence for a novel tumour suppressor role for TBX3 in fibrosarcomas where it inhibits cell proliferation, migration and tumour-forming ability." (PMID 26900951, 2016). "Interestingly, we found TBX3 to inhibit migration of fibrosarcoma cells, suggesting that it may function to either promote or inhibit tumorigenesis depending on the cellular context." (PMID 26900951, 2016). "TBX3 is regulated by AKT1 and plays a cancer-suppressive role in fibrosarcoma; TBX3 directly binds to the promoter of COL1A2, inhibiting substrate-dependent and non-substrate-independent cell proliferation, migration, and in vivo tumorigenic capacity." (PMID 38965548, 2024). "TBX3 directly binds to and activates collagen type I alpha 2 chain (COL1A2), mediating the inhibitory effect of TBX3 on fibrosarcoma cell migration." (PMID 38965548, 2024). "Compared with the normal WI38 fibroblast cells, TBX3 was upregulated in transformed (CT-1 and SV-WI38) fibroblasts as well as the naturally occurring HT1080 human fibrosarcoma cells." (PMID 26900951, 2016).
rhabdomyosarcoma (8 papers, 2016 to 2025). A rare aggressive malignant mesenchymal neoplasm arising from skeletal muscle. "A positive effect of TBX3 on cell migration was also observed in liposarcoma and rhabdomyosarcoma cells." (PMID 26900951, 2016). "We also hypothesised that the ‘hit’ drugs may inhibit endogenous TBX2 and/or TBX3 in other TBX2/3‐driven cancers including rhabdomyosarcoma (RMS)." (PMID 39403898, 2024). "This study identifies c-Myc/AKT1/TBX3 as an important axis that could be targeted for the treatment of rhabdomyosarcoma." (PMID 32098189, 2020). "We previously reported that the T-box transcription factor 3 (TBX3), which has been identified as a druggable target in many cancers, is overexpressed in rhabdomyosarcoma patient samples and cell lines." (PMID 32098189, 2020). "We have shown that TBX2 represses p21, p14/19, and PTEN in rhabdomyosarcoma (RMS) and skeletal muscle but the function and regulation of TBX3 were unclear." (PMID 30979887, 2019). "In addition, synergistic activity of TBX3, c-Myc, and AKT has been revealed in rhabdomyosarcoma." (PMID 38909034, 2024).